TRIM33 (tripartite motif containing 33)
Diseases named in the same sentence as TRIM33 in open-access papers (continued):
Sharing a sentence is not in itself a finding about the gene and the disease.
TRIM33 also shares sentences with these, for which no sentence is quoted: interstitial lung disease (16 papers); calcinosis (8); Autoimmunity (6); juvenile dermatomyositis (6); Erythema (5); nasopharyngeal carcinoma (4); ovarian carcinoma (4); Sjögren’s syndrome (4); systemic sclerosis (4); Arthritis (3); connective tissue diseases (3); idiopathic pulmonary fibrosis (3); lymphoma (3); Myalgia (3); myopathies (3); oesophageal cancer (3); Skin ulcer (3); adenocarcinoma (2); bladder cancer (2); chronic myelogenous leukemia (2); chronic myelomonocytic leukaemia (2); COVID-19 (2); endometrial cancer (2); hyperlipidaemia (2); inclusion body myositis (2); lung disease (2); Lupus (2); Pancreas (2); polymyositis (2); rectal cancer (2).
A further 66 diseases each share a sentence with TRIM33 in 2 papers or fewer.